BECN1 (beclin 1)
Diseases named in the same sentence as BECN1 in open-access papers (continued):
Sharing a sentence is not in itself a finding about the gene and the disease.
prostate carcinoma (101 papers, 2010 to 2025). A carcinoma that arises from epithelial cells of the prostate gland. "First, it was found that BECN1, the gene encoding Beclin-1 and the yeast ortholog Atg6, is monoallelically eliminated in breast, ovarian, and prostate cancers." (PMID 40248706, 2025). "Human BECN1 gene encodes for Beclin-1 protein, which is needed for autophagy, is located on chromosome 17q21, with monoallelic deletions reported in breast malignancies and ovarian and prostate cancers." (PMID 40444035, 2025). "Many Beclin-1 monoallelic deletions have been observed in breast, ovarian, and prostate cancers; the disruption of both Beclin-1 alleles results in the suppression of cell proliferation and autophagy in vivo." (PMID 38473345, 2024). "An early study indicated loss of heterozygosity of the BRCA1 loci and other loci on chromosome 17q in human prostate cancer, suggesting monoallelic loss of BECN1, which is located at 17q23.31." (PMID 38910881, 2024). "Loss of BECN1 expression was demonstrated in ovarian, breast and prostate carcinomas and is related to patient survival in breast and stomach carcinomas." (PMID 34681622, 2021). "The role of autophagy in tumorigenesis is somewhat paradoxical; on the one hand, loss of the gene essential to autophagy, Beclin-1(Atg-6), is found in many tumors, including breast, ovarian, and prostate cancers." (PMID 34201882, 2021). "For example, the monoallelic deletion of the 17q21 region, affecting the BECN1 gene, is associated with breast, ovarian and prostate cancer." (PMID 33147747, 2020). "Beclin 1 functions as a haploinsufficient tumor suppressor, and allelic loss of Beclin 1 is frequently found in sporadic breast, ovarian, and prostate cancers." (PMID 33287140, 2020). "The loss of BECN1 is a frequent event in many human tumors, including breast, ovarian, and prostate cancer, and murine Beclin-1 knock-out studies confirmed the development of spontaneous tumors in mice." (PMID 31569540, 2019). "The essential autophagy gene ATG6/BECN1 encoding the Beclin1 protein has been implicated as a tumor suppressor in breast, ovarian, and prostate cancers." (PMID 30678689, 2019). "In fact, mice that are haplo-deficient for BECN1 develop spontaneous tumors due to an impaired basal autophagy and in humans, mutations in BECN1 occur in up to 75% of breast, ovarian, and prostate cancers." (PMID 28725634, 2017). "However, a more detailed study on a larger set of patients (from the TCGA cohort) revealed that loss of BECN1 is a very rare event in prostate cancer." (PMID 38910881, 2024). "Prognosis of low KLF5 /high BECN1 expression cohort was the worst compared with the three other cohorts (p=0.0099) which suggested that the level of KLF5/BECN1 axis was significantly associated with recurrence of prostate cancer." (PMID 31534497, 2019). "Also, not only the low expression of KLF5 but the low level of KLF5/high level of BECN1 are associated with the poor prognosis of prostate cancer patients and have a potential value in precision medicine for the prognostic evaluation of patients." (PMID 31534497, 2019). "The ATG gene Beclin 1, as an important autophagy-associated signaling molecule, is mono-allelically deleted in 40–75% of human malignancies such as liver, lung, breast, ovarian, and prostate cancer." (PMID 22200845, 2012). "Monoallelic deletion of beclin 1 increased the incidence of tumor formation in mice, and the gene that encodes beclin 1 maps to a tumor susceptibility locus frequently deleted in breast, ovarian and prostate cancer." (PMID 21695150, 2011). "Thus, it is reasonable to believe that the decrease in Bcl-2 levels caused by Smp43 might co-exist with the increase in Beclin 1, which is consistent with the antitumor mechanism of licorice and licochalcone-A against human LNCaP prostate cancer cells." (PMID 37235381, 2023).
prostate carcinoma (continued). "Several research studies have been carried out, indicating a correlation between the removal of the BECN1 gene and the development of breast, ovarian, and prostate cancer." (PMID 40248706, 2025). "Deletion of BECN1 has been reported in human breast, ovarian and prostatic cancer cell lines and BECN1+/− mutant mice exhibit a high incidence of spontaneous tumours, which implies a tumour suppressor function for autophagy." (PMID 38398064, 2024). "The results of this study suggest that AMPK-Beclin-1 significantly reduces prostate cancer metastasis to the bone in human tissues." (PMID 39705435, 2024). "In patients with BPH, Beclin-1 expression was higher compared to those with prostate cancer and bone metastasis, whereas AMPK expression showed the opposite trend." (PMID 39705435, 2024). "This study aimed to examine the expression of the AMPK/Beclin-1 pathway in prostate cancer bone metastasis." (PMID 39705435, 2024). "Autophagy has been suggested to suppress tumors because alleles of the essential autophagy gene, Beclin-1 (ATG6), are lost in some human breast, ovarian, and prostate cancers." (PMID 37415741, 2023). "Several studies on ovarian, breast, and prostate cancers have reported the downregulation of Beclin 1 as a mechanism of tumor cell proliferation." (PMID 37004094, 2023). "For instance, MIR139 induces MTOR signaling, while downregulating BECN1 to inhibit autophagy flux, resulting in subsequent apoptosis induction in prostate cancer cells." (PMID 35317831, 2022). "Originally, autophagy was thought to be a purely tumor-suppressive mechanism because essential autophagy-related genes like BECN1 (ATG6) feature allelic loss in human breast-, ovarian- and prostate carcinoma." (PMID 35406408, 2022). "In the most recent study, AITC was reported to induce protective autophagy through BECN1 (beclin-1) upregulation in PC3 human prostate cancer cells." (PMID 36135016, 2022). "In contrast, a genetic knockdown of ATG5 and Beclin 1 was shown to mediate radioresistance in prostate cancer cells." (PMID 35989353, 2022). "In human cancers, autophagy was first thought to be an anti‐tumorigenic process with ATG6/BECN1 haploinsufficiency detected in approximately 45 to 70% of breast, ovarian and prostate cancers." (PMID 34725936, 2021). "BECN1 gene deletion is often present in human breast, ovarian, and prostate cancers, and aging Becn1+/- mice are prone to tumors including lymphomas and lung and liver cancers." (PMID 32765806, 2020). "Since high BECN1 level was associated with high-grade prostate cancer (GSE16560), we further investigated the regulation of BECN1 expression by KLF5." (PMID 31534497, 2019). "Currently, Beclin-1 is usually studied in the field of tumors, including ovarian, breast, and prostate cancer." (PMID 29853968, 2018). "In another study, miR-216a downregulation correlated with autophagy activation in radiation-resistant prostate cancer cells through depression of BECN1/Beclin 1, and forced expression of the miRNA led to radiosensitivity and cell death." (PMID 28459042, 2017). "The most compelling evidence for autophagy as a tumour suppressive mechanism is based on the finding that Beclin-1 (BECN1), a gene involved in autophagosome formation, has been found haploinsufficient in around 50% of breast, ovarian and prostate cancers." (PMID 27256984, 2016). "The expression of Beclin-1 was identified to be downregulated in a variety of tumor cells, such as those of breast, ovarian and prostate cancers, and gliomas." (PMID 25789037, 2015). "In PC3 and LNCaP prostate cancer cell lines therapeutic starvation with 2DG evoked autophagy judged by presence of autophagic hallmarks such as higher expression of Beclin 1 and LC3 II, together with its membrane translocation." (PMID 25821797, 2015). "One of the key proteins involved in autophagy—called BECN1—suppresses the growth of tumors, and the gene that makes BECN1 is missing in 40–70% of human breast, ovarian, and prostate cancers." (PMID 25490155, 2014).
prostate carcinoma (continued). "Beclin-1 is monoallelically deleted in a high percentage of human breast, ovarian and prostate cancers, and decreased levels of the protein have been found in human breast, ovarian and brain tumors." (PMID 24885292, 2014). "Beclin 1, the essential autophagy regulator, is monoallelically deleted in many human ovarian, breast, and prostate cancers, and targeted mutant mice with heterozygous disruption of beclin 1 are more prone to the development of spontaneous tumors." (PMID 24175288, 2013). "Beclin 1 which is required for autophagy induction is monoallelically deleted in a high percentage of human breast, ovarian and prostate cancers, and its expression suppresses the tumorigenicity of human cancer cell lines." (PMID 20184741, 2010). "In our study, AMPK-Beclin-1 significantly reduced prostate cancer bone metastasis in human tissues." (PMID 39705435, 2024). "We hypothesize that the AMPK/Beclin-1 pathway may represent a novel approach for addressing prostate cancer with bone metastasis." (PMID 39705435, 2024). "Notably, Beclin-1 levels were negatively correlated with AMPK levels in prostate cancer with bone metastasis." (PMID 39705435, 2024). "In addition, BECN1 is an important downstream target of AMPK for initiating autophagy cascades in prostate cancer cells." (PMID 36852470, 2023). "Moreover, BECN1 is a key autophagy regulator gene whose expression deletions are observed in multiple tumours, such as ovarian and prostate cancers and is thus considered a haploinsufficient tumour suppressor gene." (PMID 36852470, 2023). "Besides, docetaxel exposure downregulates KLF5 expression via an AMPK-MTOR-RPS6KB/p70S6K axis to increase BECN1 expression, leading to autophagy induction and chemoresistance features of prostate cancer cells." (PMID 35317831, 2022). "According to a recent report that KLF5 could inhibit autophagy in prostate cancer, we performed RT-qPCR to find that BECN1 was negatively correlated with KLF5 in BC." (PMID 35073911, 2022). "Additionally, silibinin and arsenic alone and in combination initiated autophagic cell death that increased the expression of the Beclin 1 protein by a higher level of ROS in the early stage of prostate cancer cell DU145 treatment." (PMID 33494431, 2021). "Another significant finding was that docetaxel treatment repressed KLF5 expression through AMPK/mTOR/p70S6K signaling pathway resulting in increased BECN1, induction of cell autophagy, and promotion of cell survival in castration-resistant prostate cancer cells." (PMID 31534497, 2019). "Monoallelic deletion of BECN1 gene was reported in 40–70% of ovarian, breast and prostate cancers." (PMID 31272261, 2019). "It was reported that BECN1 was monoallelically deleted in ovarian, breast and prostate cancers." (PMID 31272261, 2019). "Interestingly, the BECN1 gene is monoallellicaly deleted in 40%–75% of breast, ovarian, and prostate cancers." (PMID 31877888, 2019). "The allelic loss of proteins interacting with Beclin-1, such as UV radiation resistance-associated gene protein (UVRAG) and Bax-interacting factor-1, is also common in breast, gastric, colon, bladder, and prostate cancer." (PMID 31569540, 2019). "The correlation between KLF5/BECN1 levels and prostate cancer prognosis may be helpful toward precision medicine in the clinic by identifying prostate cancer patients, who are more likely to respond to docetaxel treatment." (PMID 31534497, 2019). "Conversely, other tumor types like human breast, ovarian, and prostate cancers have allelic deletions of the essential autophagy regulator Beclin 1, indicating that decreased autophagy may promote tumor development." (PMID 25821797, 2015). "BECN1 is deleted in 40–75% of human breast, ovarian, and prostate cancers." (PMID 25490155, 2014).
prostate carcinoma (continued). "The first reports connecting autophagy to cancer showed that allelic loss of the essential autophagy gene BECLIN1 (BECN1) is prevalent in human breast, ovarian, and prostate cancers and that Becn1+/- mice develop mammary gland hyperplasias, lymphomas, lung and liver tumors." (PMID 23181220, 2012). "Also, analysis of androgen-independent prostate cancer cells showed that gossypol interrupted Beclin 1 and Bcl-2/Bcl-xL interactions and that gossypol-induced autophagy was dependent on Beclin 1 and Atg5." (PMID 22240779, 2012). "Importantly, the BECN1 gene is deleted in around 50% of breast, ovarian and prostate cancer cases." (PMID 38398064, 2024). "Interestingly, we found that KLF5 could inhibit prostate cancer cell autophagy via suppressing the transcription of BECN1 cooperatively with HDAC3." (PMID 31534497, 2019). "Interestingly, KLF5 could inhibit prostate cancer cell autophagy by suppressing the transcription of BECN1 cooperatively with HDAC3." (PMID 31534497, 2019). "We examined the expression levels of Beclin-1 and AMPK in human prostate tissues by IHC and found that Beclin-1 levels were negatively correlated with AMPK in prostate cancer with bone metastasis (P < .05)." (PMID 39705435, 2024). "The study identified distinct immunohistochemical Beclin-1 results between BPH and prostate cancer with bone metastasis." (PMID 39705435, 2024). "Initially, autophagy was considered a pure cancer suppressor mechanism since basic autophagy-related genes such as BECN1 (ATG6) have allelic deletions in the human breast, ovarian, and prostate cancers." (PMID 39319052, 2024). "Therefore, knowledge of AMPK-Beclin-1 may be useful in preventing prostate cancer metastasis." (PMID 39705435, 2024). "It is worth mentioning that co-administration of 3-methyladenine as an autophagy inhibitor, enhances the potential of abiraterone in prostate cancer suppression via inducing a further decrease in LC3, ATG5 and BECN1 levels compared to abiraterone alone." (PMID 35317831, 2022). "In prostate cancer suppression, abiraterone downregulates the expression levels of LC3, ATG5 and BECN1 to inhibit autophagy." (PMID 35317831, 2022). "MIR493 upregulates PHLPP2 (PH domain and leucine rich repeat protein phosphatase 2) to promote expression of BECN1 and ATG7, resulting in autophagy and reduced ability of prostate cancer cells in colony formation." (PMID 35317831, 2022). "With regards to the radio-resistance feature of prostate cancer cells, HULC induces MTOR signaling, while it diminishes levels of BECN1, leading to autophagy inhibition." (PMID 35317831, 2022). "In cancer cells overexpressing the miR-34a show reduced expression of autophagy-related proteins, such as ATG4B, Beclin-1 and LC3B II/I in prostate cancer cells by p-AMPK down-regulation as well as up-regulation of p-mTOR." (PMID 35193115, 2022). "MIR32 is another factor that upregulates BECN1 and LC3-II, while downregulating MTOR to induce autophagy and provide radio-resistance in prostate cancer cells." (PMID 35317831, 2022). "Examination of molecular pathways demonstrates that KLF5 inhibits BECN1 and HDAC3 (histone deacetylase 3) cooperation to suppress autophagy and promote docetaxel sensitivity in the context of prostate cancer." (PMID 35317831, 2022). "In a previous study, ER stress inducers activated the Beclin-1, Atg5, and LC3-II proteins and induced cell death in colon and prostate cancer." (PMID 34443626, 2021). "FOXM1 expression was upregulated in the docetaxel resistant prostate cancer cell lines, downregulation of ATG7, Beclin 1, or cotreatment with chloroquine partly restored sensitivity to docetaxel in the FOXM1-overexpressing prostate cancer cells." (PMID 32587255, 2020). "Taken together, our results indicated that KLF5 knockdown enhances docetaxel-induced cell autophagy, and repression of BECN1 and cell autophagy is necessary for KLF5 to increase cell sensitivity to docetaxel in prostate cancer cells." (PMID 31534497, 2019).
prostate carcinoma (continued). "We further analyzed the prognosis (recurrence time) of prostate cancer patients from the TCGA database and divided the patients into four cohorts according to the expression levels of KLF5 and BECN1." (PMID 31534497, 2019). "Beclin 1 is mapped to a region approximately 150 kb to BRCA1 on chromosome 17q21, which is usually deleted in breast, ovarian and prostate cancer." (PMID 20230646, 2010). "Previous study reported that in prostate cancer cells, KLF5 could collaborate with HDAC3 to repress BECN1 transcription." (PMID 40659605, 2025). "MIR34A-loaded chitosan nanoparticles stimulate autophagy in prostate cancer cells independent of BECN1, ATG4, ATG5 and ATG7, known as non-canonical autophagy." (PMID 35317831, 2022). "In addition, reduced BECN1/Vps15/Vps34 complex activity mediated by the interaction of BECN1 with androgen receptor can inhibit ERK-mediated growth factor signaling and suppress the growth of castration-resistant prostate cancer." (PMID 34681622, 2021). "However, Beclin‐1, an autophagy protein which is involved in the early stage of autophagosome formation, was down‐regulated in NDV/FMW‐infected prostate cancer cells at 24 and 48 hpi, suggesting inhibition of autophagy." (PMID 32100392, 2020). "Thus, repression of BECN1 and cell autophagy was critical for KLF5 to increase the sensitivity of prostate cancer cells to docetaxel." (PMID 31534497, 2019). "Our results indicate that in prostate cancer, docetaxel treatment represses KLF5 expression through AMPK/mTOR/p70S6K signaling pathway, which may lead to increase of BECN1, induction of cell autophagy, and promotion of cell survival." (PMID 31534497, 2019). "In prostate cancer, docetaxel treatment repressed KLF5 expression via AMPK/mTOR/p70S6K signaling pathway, which may lead to increased BECN1 expression, induction of cell autophagy and promotion of cell survival." (PMID 31534497, 2019). "This study suggests that the AMPK/Beclin-1 pathway may regulate osteoclastic activity through the autophagy pathway, promoting bone metastasis in prostate cancer cells without affecting the neuroendocrine phenotype." (PMID 39705435, 2024). "Similarly, TQ treatment may induce cell autophagy by increasing the LC3‐II/LC3‐I ratio and Beclin‐1 expression rather than direct induction of apoptosis in the docetaxel‐resistant human prostate cancer PC3 cell line." (PMID 36176197, 2023). "BECN1 mRNA also poses AREs at its 3′UTR, and upon starvation HuR stimulates BECN1 translation in non-cancerous keratinocyte, in breast and prostate cancer cells, and in human and rat liver stellate cells." (PMID 32232004, 2020).